MEG3 (maternally expressed 3)
Diseases named in the same sentence as MEG3 in open-access papers (continued):
Sharing a sentence is not in itself a finding about the gene and the disease.
cervical carcinoma (continued). "Although MEG3 is expressed in many normal tissues, it is lost in an expanding list of human cancers such as non-small cell lung cancer, cervical cancer and bladder cancer." (PMID 29287592, 2017). "More important, Multivariate survival analysis further demonstrated that hypermethylation of MEG3 in plasma was an independent prognostic marker indicating poorer RFS for cervical cancer patients." (PMID 28740189, 2017). "More important, we observed a decrease in methylation level of MEG3 promoter after operation in plasmas of cervical cancer patients (P < 0.001)." (PMID 28740189, 2017). "To investigate the role of promoter methylation in regulation of MEG3 expression in cervical cancer cells, we examined the effect of 5-aza-CdR on promoter methylation levels and MEG3 expression." (PMID 28057015, 2017). "The results also indicate that inactivation of MEG3 via promoter hypermethylation plays an important role in regulation of cervical cancer cell proliferation." (PMID 28057015, 2017). "Then we identified the epigenetic regulation of MEG3 expression in cervical cancer tissues and cells." (PMID 28057015, 2017). "However, the diagnostic and prognostic value of MEG3 for cervical cancer remains unknown." (PMID 28057015, 2017). "We also observed that the level of MEG3 methylation in plasma was lower than that in cervical cancer tissues." (PMID 28740189, 2017). "We first performed ROC curve and Cox regression analyses to determine the clinical value of MEG3 in patients with cervical cancer." (PMID 28057015, 2017). "Lastly, we demonstrated that MEG3 methylation in plasma was a prognostic factor for cervical cancer patients." (PMID 28740189, 2017). "Together, these results were to identify the clinical significance of plasma MEG3 methylation in cervical cancer." (PMID 28740189, 2017). "Collectively, these results indicate the importance of MEG3 methylation in cervical cancer progression." (PMID 28057015, 2017). "The aberrant methylated pattern (M) of MEG3 promoter was observed in 53.6% (90 of 168) of plasma samples of cervical cancer patients." (PMID 28740189, 2017). "Similar to other findings, low MEG3 expression was shown to be related to hypermethylation of the MEG3 promoter in cervical cancer tissues." (PMID 28057015, 2017). "That indicates that MEG3 shows excellent potential value for clinical work, especially for cervical cancer, in which biopsy is routine before therapy." (PMID 28057015, 2017). "The area under the ROC curve (AUC) was 0.867 according to level of MEG3 methylation in plasma for the diagnosis of cervical cancer." (PMID 28740189, 2017). "In a recent study, the down-regulated MEG3 in cervical cancer has been shown to affect cell proliferation and apoptosis through modulating the level of miR-21-5p." (PMID 29069869, 2017). "With regard to combined level of MEG3 methylation in plasma and prognosis, we divided the cervical cancer patients into 2 groups: group 1, methylated group (n = 90); group 2, partially methylated (M and U) and unmethylated group (n = 78)." (PMID 28740189, 2017). "In this study, we investigated the relationship between MEG3 and cervical cancer based on the results of our previous study." (PMID 28057015, 2017). "ROC curve analysis indicated that MEG3 status showed sufficient sensitivity and specificity for prediction of tumor size and lymph node metastasis in patients with cervical cancer." (PMID 28057015, 2017). "The presence or absence of lymph node metastasis is a crucial factor in therapy decision-making for patients with cervical cancer and our study found that MEG3 is a good candidate to predict it." (PMID 28057015, 2017). "The results of qRT-PCR analysis showed that MEG3 expression was significantly lower in cervical cancer tissues compared to corresponding normal tissues, consistent with our previous study." (PMID 28057015, 2017).
cervical carcinoma (continued). "We first provided evidences to support that MEG3 promoter was hypermethylation not only in cervical cancer tissues, but also in plasmas of cervical cancer patients." (PMID 28740189, 2017). "To better understand the role of methylation, we also analyzed the correlation between MEG3 expression and promoter methylation level in cervical cancer tissues." (PMID 28057015, 2017). "In this study, we aimed to further elucidate the role and potential inactivation mechanism of MEG3 in cervical cancer." (PMID 28057015, 2017). "LcnRNAs of HOTAIR, CCAT2, MALAT1, EBIC and MEG3 have been reported to be involvled in cervical cancer metastasis." (PMID 27736969, 2016). "Ectopic expression of MEG3 inhibits the proliferation of cervical carcinoma cells through the induction of cell cycle arrest and apoptosis." (PMID 26485761, 2015). "Besides being a tumor suppressor, MEG3 inhibits the proliferation of cervical cancer cells by promoting the ubiquitination-mediated degradation of P-STAT3 protein." (PMID 40242248, 2025). "In addition, by modulating the miR-21/PTEN axis, MEG3 promoted cisplatin sensitivity in cervical cancer cells." (PMID 40242248, 2025). "In addition, MEG3 operates as a cancer suppressor by reducing the levels of miR-21-5p in cervical cancer cell lines." (PMID 40242248, 2025). "MEG3 is consistently expressed at low levels in cervical cancer tissues and cell lines." (PMID 40242248, 2025). "Additionally, MEG3 induced apoptosis in cervical carcinoma cells through endoplasmic reticulum stress and the miR-7-5p/STC1 axis." (PMID 40242248, 2025). "In addition, hypermethylation of MEG3 in plasma was related to worse recurrence-free survival and OS in patients with cervical cancer." (PMID 38110977, 2023). "The hypermethylation of the MEG3 promoter was also observed in cervical cancer and NSCLC." (PMID 36851033, 2023). "Obviously, MEG3 was downregulated in cervical cancer tissues compare with normal cervical tissues." (PMID 36344947, 2022). "We demonstrated that MEG3 was down-regulated in cervical cancer by analyzing the TCGA database." (PMID 36344947, 2022). "Furthermore, cervical cancer cells undergo increased apoptosis and growth suppression after MEG3 upregulation, confirming its role in tumor suppression in this type of cancer." (PMID 34204445, 2021). "Likewise, MEG3 is also downregulated in cervical cancer when compared to the adjacent normal tissues, and there is a negative correlation with tumor size, FIGO stage, lymphatic metastases, infection with human papilloma virus (HPV), and miR-21 expression." (PMID 34204445, 2021). "Expression of MEG3 is low both in cervical cancer tissues and in cervical cancer cell lines." (PMID 32154165, 2020). "Therefore, the abnormality of the regulatory network of MEG3 gene expression is closely related to the occurrence and development of cervical cancer." (PMID 31320837, 2019). "Therefore, this study aimed to explore the mechanism of action of MEG3 in cervical cancer based on our previous studies." (PMID 31320837, 2019). "Upregulation in MEG3 expression was shown to inhibit the proliferation of cervical cancer cells and promote apoptosis, while MEG3 downregulation could promote the proliferation of cervical cancer cells and inhibit their apoptosis." (PMID 31320837, 2019). "The hypermethylation of MEG3 gene promoter may result in low expression of MEG3 in cervical cancer, eventually leading to the proliferation of malignant cells and decrease in cell apoptosis." (PMID 31320837, 2019). "Through RNA pull-down and RIP assays, we confirmed that MEG3 could directly bind to P-STAT3 protein in cervical cancer cell lines and exert its regulatory effect." (PMID 31320837, 2019). "We performed a tumor formation experiment in nude mice and found that MEG3 could significantly inhibit the growth of cervical cancer cells in nude mice." (PMID 31320837, 2019).
cervical carcinoma (continued). "In vitro study results have shown that the low expression of MEG3 may lead to the malignant proliferation of cervical cancer cells." (PMID 31320837, 2019). "Maternally expressed 3 (MEG3) plays an important role in cervical cancer development, but its exact role remains unclear." (PMID 31320837, 2019). "The in-depth elaboration of the MEG3-STAT3 regulatory axis in cervical cancer may clarify the mechanism of action of MEG3 and provide new ideas for cervical cancer treatment." (PMID 31320837, 2019). "It was also confirmed that MEG3 could decrease the level of P-STAT3 protein in cervical cancer cell lines." (PMID 31320837, 2019). "Exosomal lncRNA MALAT1, HOTAIR, and MEG3 are differentially expressed in cervical cancer cervicovaginal lavage samples, which suggests that these lncRNAs can be promising biomarkers in detecting cervical cancer." (PMID 31360701, 2019). "The effect of MEG3 on tumor formation ability of cervical cancer cells was determined in nude mice." (PMID 31320837, 2019). "lnc-RNA MEG3 is negatively relevant with FIGO stages, tumor size, lymphatic metastasis, and HR-HPV infection, and downexpressed MEG3 in cervical cancer reduces the inhibition effect on miR-21-5p expression, which leads to less apoptosis and more proliferation of cancer cells." (PMID 29850477, 2018). "We first confirmed the reliability of MEG3 methylation in plasma of cervical cancer patients." (PMID 28740189, 2017). "MEG3 is a powerful tool for diagnosis and prognosis of patients with cervical cancer, and low expression of MEG3 is likely to be related to promoter hypermethylation in cervical cancer." (PMID 28057015, 2017). "Furthermore, univariate analysis of RFS revealed that the level of MEG3 methylation in plasma was a prognostic indicator for cervical cancer patients." (PMID 28740189, 2017). "Furthermore, we altered the methylation status of the MEG3 promoter in two cervical cancer cell lines (HeLa and CaSki) using a DNA methylation transfer enzyme inhibitor (5-Aza-CdR), to investigate whether promoter hypermethylation is a potential cause of MEG3 inactivation." (PMID 28057015, 2017). "In conclusion, plasma MEG3 methylation may be a reliable diagnostic biomarker for the early stage, HR-HPV infection and lymph node metastasis of cervical cancer." (PMID 28740189, 2017). "In this study, we tested the hypothesis that promoter hypermethylation may be able to reduce MEG3 levels in cervical cancer, by evaluating the methylation level of the MEG3 promoter and its effects on MEG3 expression." (PMID 28057015, 2017). "In summary, we provided strong evidences supporting that plasma MEG3 methylation could be a candidate of biomarker for cervical cancer." (PMID 28740189, 2017). "In summary, we propose that the following process may occur in cervical cancer cells: promoter hypermethylation → inactivation of MEG3 → malignant cell proliferation." (PMID 28057015, 2017). "Therefore, the methylation status of MEG3 in plasma is a potential novel epigenetic biomarker which has great value in the clinical practice of cervical cancer." (PMID 28740189, 2017). "Further investigation demonstrated that over-expression of MEG3 promotes apoptotic cell death and induces G2/M cell cycle arrest in cervical cancer (HeLa) and retinoblastoma (C33A) derived cell lines through the decrease of CDK1 (cyclin-dependent Kinase 1) and CCNB1 (cyclin B1) levels." (PMID 29069869, 2017). "However, no reports have been published to date on the relationship between promoter methylation and MEG3 expression in cervical cancer." (PMID 28057015, 2017). "Moreover, recent studies also showed that promoter methylation plays a major role in silencing of the MEG3 gene in pituitary tumor, meningiomas, cervical cancer and neuroblastoma cell lines." (PMID 29287592, 2017).
cervical carcinoma (continued). "Moreover, the methylation level of MEG3 in the plasmas of cervical cancer patients with lymph node metastasis was significantly higher compared with those without metastasis (P < 0.001)." (PMID 28740189, 2017). "In addition, growth suppression and increased apoptosis of cervical cancer cells is observed after MEG3 upregulation, which demonstrates its tumor suppressive role in this cancer." (PMID 28637507, 2017). "In addition, Chi-square test also showed that hypermethylation of MEG3 promoter in plasma was a risk factor not only for CIN III and cervical cancer, but also HPV infection and lymph node metastasis." (PMID 28740189, 2017). "Further, we endeavored to reveal the role of MEG3 methylation in the progress of cervical cancer." (PMID 28057015, 2017). "For CIN III is a premalignant lesion of cervical cancer, our result implied that plasma MEG3 methylation might have great value in early diagnosis of cervical cancer." (PMID 28740189, 2017). "Besides, XLOC_010588, XIST, LET, MEG3 were correlated to poor prognosis with the low expressions of lncRNAs in cervical cancer." (PMID 28977961, 2017). "Moreover, hypermethylation of the MEG3 promoter was observed in most cervical cancer tissue samples, and demethylation of the MEG3 promoter led to re-expression of MEG3 and inhibited proliferation of HeLa and CaSki cells." (PMID 28057015, 2017). "Moreover, our results indicated that a decrease in the methylation level resulted in not only re-expression of MEG3, but also reduction of the proliferation potential in cervical cancer cells." (PMID 28057015, 2017). "However, increasing the MEG3 levels in cervical cancer cell lines can have significant effects." (PMID 40242248, 2025). "However, the regulatory proteins acting downstream of MEG3 in cervical cancer cells are unknown, demanding further investigation." (PMID 31320837, 2019). "Similarly, we found that MEG3 can regulate the level of P-STAT3 and c-Myc simultaneously in cervical cancer cells, indicating that MEG3 might regulate the expression of c-Myc through P-STAT3 indirectly." (PMID 31320837, 2019). "Interestingly, we noted that the role of MEG3 methylation was consistent with that of MEG3 expression in cervical cancer, and the clinical characteristics of patients in the methylated group were similar to those of patients in the MEG3-Low group, according to our previous study." (PMID 28057015, 2017). "In addition, it confirms the results of our previous study, that down-regulation of MEG3 could suppress the proliferation of cervical cancer cells in another way." (PMID 28057015, 2017). "Thus, plasma MEG3 methylation may be useful as a prognostic marker for the prediction of relapse and survival in cervical cancer patients." (PMID 28740189, 2017). "However, the diagnostic and prognostic values of MEG3, as well as the molecular mechanism of MEG3 inactivation in cervical cancer, remain unclear." (PMID 28057015, 2017). "Low MEG3 levels, lymph node metastasis, and advanced FIGO stage (III and IV) have been identified as independent cervical cancer prognostic factors." (PMID 40242248, 2025). "Several lncRNAs MEG3, TUSC8, CRNDE, have been shown to act as tumour suppressors in cervical cancer." (PMID 39912983, 2025). "The negative correlation of MEG3 with CDKN2A is consistent with literature reports that suggest that the downregulation of MEG3 and overexpression of CDKN2A in cervical cancer is involved in disease progression." (PMID 37628839, 2023). "This suggests that MEG3 inhibits cervical cancer progression by regulating PI3K/AKT/Bcl-2/Bax/P21 and PI3K/AKT/MMP-2/9 signaling pathways in cervical cancer." (PMID 36890809, 2023).
cervical carcinoma (continued). "LncRNAs MEG3, CRNDE, LINP1 and SNHG20 are shown to influence cervical cancer progression and we report G4 specific protein partners for these lncRNAs." (PMID 37628839, 2023). "After sorting the data, we selected MEG3, TIMP3, DAPK1, and SOX1 as being the most hypermethylated genes specific for the incipient stages of cervical carcinoma, while MLH1 and MALAT1 were chosen as the most hypomethylated genes." (PMID 35682732, 2022). "In cervical cancer, HOTAIR and MALAT1 were upregulated and MEG3 was downregulated within the cervicovaginal lavage in cervical cancer patients." (PMID 34067896, 2021). "We analyzed the role of MEG3 and STAT3 in cervical cancer and found that these two proteins have overlapping functions in HPV infection and lymphatic metastasis." (PMID 31320837, 2019). "Cervical cancer cells were divided into MEG3 shRNA + dimethyl sulfoxide (DMSO) group, MEG3 shRNA + niclosamide group, NC shRNA + DMSO group, and NC shRNA + niclosamide group." (PMID 31320837, 2019). "Clone formation assay and flow cytometry analysis results revealed that the inhibitory effect of MEG3 on P-STAT3 promoted apoptosis and inhibited proliferation of cervical cancer cells." (PMID 31320837, 2019). "Our previous study showed that MEG3 expression levels are related to HR-HPV infection, tumor size, FIGO stage, and lymph node metastasis in patients with cervical cancer." (PMID 28057015, 2017). "Univariate analysis showed that MEG3 expression, differentiation, FIGO stage, and lymph node metastasis were all prognostic factors for recurrence-free survival in patients with cervical cancer." (PMID 28057015, 2017). "Several studies reported that multiple lncRNAs were dysregulated in HCC and cervical cancer, such as HOTAIR and MEG3." (PMID 26147888, 2015). "In contrast, the long-chain non-coding MEG3, ZNF667-AS1, was underexpressed in cervical cancer." (PMID 36890809, 2023). "The MEG3 methylation level in local tissues and plasma of cervical cancer patients was significantly higher than those in adjacent normal tissues and healthy participants’ plasma." (PMID 38110977, 2023). "In addition, compared with normal cervical tissues, the expression of MEG3 in EMT, Hormone, and PI3K-AKT subtypes of cervical cancer tissues was significantly lower." (PMID 36344947, 2022). "In this study, we analyzed MEG3 expression levels in cervical cancer from the TCGA database by using the GEPIA visual online analysis tool, and the results showed that MEG3 expression levels were significantly lower in cervical cancer than in normal tissues." (PMID 36344947, 2022). "In conclusion, this study shows that MEG3 enhances cisplatin sensitivity in cervical cancer cells by regulating the miR-21/PTEN axis, and that MEG3 acts as a ceRNA of the miR-21/PTEN axis to exert oncogenic effects and influence cisplatin resistance in cervical cancer." (PMID 36344947, 2022). "In conclusion, MEG3 may bind to P-STAT3 protein to promote its degradation via ubiquitination, thereby inhibiting cell proliferation and affecting the development of cervical cancer." (PMID 31320837, 2019). "To determine whether the regulation of P-STAT3 protein by MEG3 affects the proliferation and apoptosis of cervical cancer cells, we reversed the regulation of P-STAT3 protein by MEG3 using a STAT3 protein phosphorylation inhibitor niclosamide." (PMID 31320837, 2019). "Based on this, we examined the expression of STAT3 and MEG3 in cervical cancer tissues and found a negative correlation between them." (PMID 31320837, 2019).